CDH23 (cadherin related 23)
Diseases named in the same sentence as CDH23 in open-access papers (continued):
Sharing a sentence is not in itself a finding about the gene and the disease.
deafness (87 papers, 2008 to 2025). An inherited or acquired condition characterized by the complete loss of the ability to hear from one or both ears. "For example, the CDH23 mutation in waltzer mice manifests as hearing and vestibular function loss, while the V2360E missense mutation carried by jera mice only results in deafness, supporting its role as a DFNB12 model." (PMID 41049429, 2025). "In summary, the study of deafness mechanisms caused by mutations in CDH23 and PCDH15 has progressed from the identification of functional mutations to in-depth investigations of structure-function relationships." (PMID 41049429, 2025). "First, we targeted the splice donor site of intron 2 within the cdh23 gene, which is associated with non-syndromic autosomal recessive deafness." (PMID 38965236, 2024). "Some of these hearing loss or deafness genes have also been identified as candidate echolocation genes, such as CDH23 and LRP2." (PMID 38672325, 2024). "The screening for deafness-causing genes then continued with targeted capture next-generation sequencing, revealing 2 novel variants of CDH23 responsible for deafness in this patient." (PMID 39287240, 2024). "ATP2B2 (encoded by PMCA in flies), which corresponds to a known genetic interactor of CDH23 that has shown to be implicated in deafness, was also localized ubiquitously throughout Johnston’s organ." (PMID 38412189, 2024). "By utilizing targeted capture next-generation sequencing to further screen for deafness-related genes, 2 novel variants in CDH23 were identified as the causative factors for the patient's deafness." (PMID 39287240, 2024). "Mutations in CDH23 cause non-syndromic autosomal recessive deafness (DFB12) and Usher Syndrome Type 1D (USH1D)." (PMID 37575969, 2023). "CDH23 is the first gene that has been proven to be related to susceptibility to noise-induced hearing loss (NIHL) in human deafness." (PMID 37575969, 2023). "In this study, a congenital deafness family, whole exome sequencing revealed a new mutation in the pathogenic gene CDH23, subsequently; the mutation has been validated using Sanger sequencing method." (PMID 37575969, 2023). "The method also correctly predicted the heterozygous deletion c.8371delC (CDH23 in NM_022124) in a fetus at risk of deafness." (PMID 35846127, 2022). "As described in “Results”, through the screening for 63 deafness genes in this study, we focused on patients with CDH23 variants." (PMID 35020051, 2022). "Here, we reported the identification of four novel variants in the CDH23 gene, which significantly expanded the mutation spectrum of CDH23-associated non-syndromic autosomal recessive deafness." (PMID 36468022, 2022). "C57BL/6 mice are homozygous for a recessive mutation in Cdh23, which is postulated to account for much of the age-onset deafness observed in the strain." (PMID 35473764, 2022). "A possible explanation is that deafness-related CDH23 mutations are caused by either homozygous or compound heterozygous mutations." (PMID 36359740, 2022). "Targeted NGS of 127 hearing loss‐related genes was carried out in the 9 probands, which allowed us to detect 5 reported and 5 novel variants in 6 distinct deafness genes including CDH23, GIPC3, MYO7A, TRIOBP, TECTA, and OTOF." (PMID 32864763, 2020). "Erl mice have the Cdh23erl/erl mutation which confers non-syndromic autosomal recessive deafness by altering the CDH23 protein in the upper part of the tip-link in HCs." (PMID 32760249, 2020). "Recent comprehensive next‐generation sequencing (NGS) analysis has helped clarify genetic epidemiology; i.e., GJB2 is the predominant deafness‐causing gene, with the other common genes being CDH23, SLC26A4, MYO15A, COL11A2, and MYO7A." (PMID 32027099, 2020). "Those deafness-associated genes included well-known HC genes, such as Cdh23 (Cadherin-23) and Cib2 (calcium and integrin binding family member 2), which were also detected in one previous single-cell SGN RNA-Seq study." (PMID 31913118, 2020).
deafness (continued). "Using this construct, we additionally characterized the D101G deafness-related mutation, which is known to affect this CDH23 region’s conformation and dynamics, as a consequence of a reduced Ca2+ binding." (PMID 31527607, 2019). "This CKK binding motif (CBM) is adjacent to the domain that interacts with harmonin, a binding partner of CDH23 implicated in deafness." (PMID 27349180, 2016). "As a novel mutation of the Cdh23 gene, the erl mutant mice exhibited the postnatal onset of hearing loss starting at P27, which progressed to total deafness at ~P100." (PMID 27882946, 2016). "A form of non-syndromic recessive deafness caused by mutations in CDH23 is classified as DFNB12 (OMIM entry 601386), where the hearing loss is moderate to profound and progressive." (PMID 26664958, 2015). "The advent of NGS rapidly led to identification of CDH23 as a cause of deafness, especially in East Asians." (PMID 26264712, 2015). "CDH23 or PCDH15 were included in our study set of genes due to their known causal roles in inherited forms of deafness." (PMID 26264041, 2015). "Recently, a similar allelic hierarchy has been reported for change affecting CDH23 function: a ‘nonsyndromic deafness' CDH23 allele in trans configuration with a ‘syndromic/Usher syndrome type I' CDH23 allele preserves vision and balance in deaf individuals." (PMID 25649381, 2015). "Many deafness mutations in CDH23 are in the calcium-binding motif of the linker region between EC repeats." (PMID 24767429, 2014). "Mutations in SLC26A4, MYO15A, and CDH23 are also reported to be frequent and important causes of deafness." (PMID 23967202, 2013). "Like the mouse USH1 models, several zebrafish lines with mutations in USH1 genes also exhibit profound deafness and balance defects, including myosin 7a (myo7a), pcdh15a, and cdh23." (PMID 22977299, 2012). "The Cdh23 locus has also been shown to modify the deafness caused by the Mass1frings mutation in BUB/BnJ strain mice and can account for the phenotypic manifestations differences observed between Frings (Cdh23753G) and BUB/BnJ (Cdh23753A)." (PMID 21119891, 2010). "Recessive mutations in genes coding for cadherin 23 (Cdh23) and protocadherin 15 (Pcdh15) cause deafness in both mice and humans." (PMID 21119891, 2010). "Although some data indicate that cdh23 is a developmental protein that disappears shortly after the onset of hearing, mutations in cdh23 disrupt hair-bundle organization and give rise to deafness and vestibular dysfunction in waltzer mice." (PMID 19320974, 2009). "The patient’s CDH23 abnormality is the likely cause of his deafness." (PMID 40760574, 2025). "This CDH23 variant was previously reported in hearing loss using a comprehensive deafness proteome." (PMID 38785568, 2024). "Missense mutations in genes, including CDH23, may represent a common etiology of deafness, depending on the mutational site within the protein." (PMID 39287240, 2024). "Studies of a DFNB12 mouse model (erl mouse) in which deafness is caused by a Cdh23 point mutation revealed that expression of BiP and CHOP in outer hair cells (OHCs), SGNs, and stria vascularis increased significantly, and confirmed that apoptosis was inhibited significantly after CHOP knockout." (PMID 39744539, 2024). "A comprehensive understanding of disease mechanisms in CDH23‐associated disorders may significantly impact the diagnosis and management of HL and deaf‐blindness worldwide." (PMID 38534090, 2024). "First, some genes may be causative for both USH and isolated deafness or RP, for example CDH23 (OMIM 605516, USH and isolated SNHL OMIM 601386)." (PMID 35226187, 2022). "Conversely, missense mutations in CDH23 are associated with non-syndromic DFNB12 deafness." (PMID 36504663, 2022). "Mutations in CDH23 have been found to be causal for the recessive autosomal deafness locus DFNB12." (PMID 34847940, 2021). "Cadherin-related 23 (CDH23) is one of the listed deafness causative genes." (PMID 32115674, 2020).
deafness (continued). "Defective CDH23 have been associated mostly with prelingual severe-to-profound sensorineural hearing loss (SNHL) in either syndromic (USH1D) or non-syndromic SNHL (DFNB12) deafness." (PMID 32115674, 2020). "Interestingly, mutations in the CDH23 gene of the cell adhesion domain result in deafness and hearing loss is closely associated with FAS." (PMID 29997484, 2018). "In homozygous waltzer mice, mutations in Cdh23 cause profound deafness and vestibular dysfunction." (PMID 21119891, 2010). "Expanding screening via next-generation sequencing (NGS) to include other established (e.g., MYO15A, OTOF, CDH23, TMC1) and emerging deafness genes would significantly enhance diagnostic yield and capture a broader spectrum of genetic causes." (PMID 41181184, 2025). "Further efforts are needed to analyze other frequent deafness-predisposing genes, such as TMC1, USH2A, CDH23 and MYO15A in an expanded panel in future studies." (PMID 36389375, 2022). "The 15 associations included a missense lead variant in TMPRSS3, a known cause of Mendelian hearing loss, adding to the tally of Mendelian deafness genes (EYA4, CDH23, TRIOBP) showing common coding-variant associations with hearing loss in adult humans." (PMID 35661827, 2022). "CDH23 is associated with Usher syndrome type ID (USH1D, OMIM #601067) and nonsyndromic autosomal recessive deafness 12 (OMIM #601386)." (PMID 35761346, 2022). "The murine ortholog, which carries a Cdh23 null allele, gives rise to waltzer phenotype and leads to disorganized, splayed stereocilia, and mimic USH1D exhibiting deafness and vestibular dysfunction." (PMID 33316915, 2020). "It is concluded that in addition to novel mutations in MYO7A, TH and EVC2, the CDH23 and GJB2 can also be responsible for deafness in the family with consanguineous marriages." (PMID 30881389, 2019). "The use of inherited disease genes sequencing panel identified the causative and novel variants in deafness related genes (GJB2, MYO7A, CDH23, TH and EVC2) in deaf brothers." (PMID 30881389, 2019). "In the current study, we detected one reported and six novel mutations in 5 distinct deafness genes (TRIOBP, LHFPL5, CDH23, PCDH15, and MYO7A) in 5 recessive families." (PMID 29568747, 2018). "Another prominent gene responsible for human recessive non-syndromic deafness is that for the protein cadherin 23 (CDH23, OMIM entry 605516)." (PMID 26664958, 2015). "The syntenic canine gene for cadherin 23 (CDH23), which causes the human non-syndromic recessive deafness DFNB12 and USH1D, was predicted to reside on the identified CFA4 segment." (PMID 26664958, 2015). "The most frequent causative gene revealed by this technology was CDH23 (n = 3), followed by MYO15A (n = 2), MYO7A (n = 2) and other four deafness genes (PCDH15 (n = 1), USH2A (n = 1), MYO3A (n = 1) and ACTG1 (n = 1))." (PMID 25373420, 2014). "Thus, Cdh23 may be an important gene that may not only underlie certain forms of congenital deafness but also age-related hearing loss and has the potential to genetically interact with other deafness genes to affect hearing." (PMID 21119891, 2010). "The Human Gene Mutation Database indicated that NCSS and nonsense mutations in CDH23 could cause both USH1D and DFNB12 deafness." (PMID 39777619, 2025). "In the present study, we have also identified the missense/non-sense heterozygous variants in the OTOG p.(Val1813Gly), SLC26A4 p.(Tyr556∗) CDH23 p.(Ala1631Val), GJB2 p.(Arg165Trp), and MYO15A p.(Arg1965His) genes which are predominant to cause deafness among Indian populations." (PMID 34113375, 2021). "This study presents a HL family GCUFAHL38, in which five different deafness genes (GJB2, SLC26A4, CDH23, MPDZ, KCNQ4) rare variants were co-segregating in different configurations, and thus further highlights the genetic complexity of hearing disorders in highly inbred families." (PMID 34946889, 2021).
deafness (continued). "The most frequent causative deafness gene was TMC1 (DFNA36) (3 cases), followed by the next tier of genes (2 cases each) (CDH23, COCH, SLC26A4, TMPRSS3, ATP1A3), and the genes that were detected only once (ACTG1, GJB2, ILDR1, MYO7A, MYO15A, NF2, NLRP3 and SERPNB6)." (PMID 32238869, 2020). "With regard to the responsible gene, the most frequent causative gene was GJB2 (29%), followed by SLC26A4 (9%), CDH23 (7%), MYO7A (4%), OTOF (5%), MYO15A (3%), and LOXHD1 (2%), indicating that these deafness genes are typical deafness genes found in the prelingual CI/EAS patients." (PMID 32027099, 2020). "The three additional variations in CDH23 might be in favor of profound deafness in elder brothers as he was deafer comparatively." (PMID 30881389, 2019). "It is suggested that the three additional variations in CDH23 might be in favor of more deafness in elder brother because his hearing ability was less than the younger brother." (PMID 30881389, 2019). "Ethnic diversity of genetic variance has been reported in deafness gene CDH23." (PMID 30123251, 2018). "We found that larvae homozygous for either of two different cdh23 mutations have morphologically normal retinas and normal visual function (assessed by measuring the optokinetic response, OKR), despite both having severe deafness and balance defects." (PMID 22977299, 2012). "Like the other USH mouse models, Cdh23 mutants have been successfully used to understand the deafness component of this disease, showing that CDH23 makes up part of the tip link in sensory hair cells, a structure that is crucial for the proper mechanotransduction of sound waves." (PMID 22977299, 2012). "According to the HGMD database, about 89.0% of the variants in CDH23 gene, 85.0% of the variants in TECTA gene, and 69.4% of the variants in OTOF gene are missense mutations, which reminds us that the missense mutations in deafness causative genes should be given more consideration." (PMID 36597107, 2023). "Despite the genetic heterogeneity, some genes showed greater contribution to cases of autosomal recessive deafness in our study: GJB2, CDH23 (10.34%), MYO15A (7%), OTOF (7%), and USH2A (7%)." (PMID 39498320, 2024). "Those in TMC1, CDH23, LOXHD1 and USH2A were each detected in two probands, and those in 10 other deafness genes were each detected in one proband." (PMID 35062939, 2022). "The gene CDH23 is located in 10q21–q22, a region containing the human deafness loci DFNB12 and USH1D." (PMID 35076463, 2022). "In our previous study, MYO15A pathogenic variant was reported at a frequency of 2.1% in nonsyndromic autosomal recessive deafness, which was the fourth most common deafness gene in Korea, following SLC26A4, GJB2 and CDH23." (PMID 29482514, 2018). "Across species, the genes identified with deafness or white pigmentation patterns include MITF, PMEL, KIT, EDNRB, CDH23, TYR, and TRPM1 in dog, cat, horse, cow, pig, sheep, ferret, mink, camelid, and rabbit." (PMID 26664958, 2015). "CDH23 is located in a region containing the human deafness loci DFNB12 and USH1D." (PMID 27520957, 2016). "Thus, through this analysis, the molecular etiology of deafness was confirmed in 23.56% (90/382) of the patients, and it involved the GJB2, SLC26A4, CDH23, MYO15A, and MT-RNR1 genes." (PMID 27018795, 2016). "These mutations in CDH23 and OTOF were only found in respectively patients 1–2 and 4 and not in the other analyzed deafness samples (e.g. we often did find the same SNP’s in different patients)." (PMID 22607986, 2012). "For CDH23 variants, younger implantee (SH62-147) showed outstanding performance compared with an older implantee (SB116-218), who underwent CI at 72 years, even though their deafness duration was not significantly different." (PMID 32238869, 2020).
deafness (continued). "In addition, mutations in MYO7A, USH1C, DFNB31, CIB2, CDH23 and PCDH15 were also reported in non-syndromic deafness without retinal degeneration and mutations in USH2A and CLRN1 have been reported in patients with isolated RP or retinal dystrophies and no deafness." (PMID 25211151, 2014).
hearing loss (82 papers, 2010 to 2026). "For example, mutations in the gene that encodes cadherin 23 (CDH23) show an increased frequency in persons with high-frequency hearing loss." (PMID 39663846, 2025). "Among these elements, we identified six potential variants in cis-regulatory elements associated with hearing loss genes, CDH23, OTOF, MYO6, COL4A4 and WHRN." (PMID 40164689, 2025). "For example, double heterozygosity for mutations in Cdh23 and Pcdh15, another tip-link component, significantly increases susceptibility to hearing loss." (PMID 40360853, 2025). "Patients with CDH23 mutations displayed a wide range of hearing loss and RP phenotypes, varying in severity, age at onset, type, and the presence or absence of vestibular areflexia." (PMID 39777619, 2025). "Our previous results provided valuable insights into the mechanisms underlying congenital hearing loss associated with CDH23 mutations." (PMID 40429749, 2025). "Defects in CDH23 disrupt these processes, resulting in sensorineural hearing loss and visual impairment." (PMID 40149483, 2025). "Nonetheless, 2 novel missense mutations of CDH23 were identified, suggesting a potential association with hearing loss." (PMID 39287240, 2024). "A statistically significant association was found between the CDH23 variants and hearing loss (one-sided Fisher’s exact test P = 0.04)." (PMID 39572598, 2024). "Other studies also indicated that, apart from GJB2, pathogenic variants in SLC26A4, MYO15A, OTOF, and CDH23 are a frequent cause of hearing loss in European populations (Hilgert, Smith, Van Camp, 2009)." (PMID 39498320, 2024). "The CDH23 gene, known for its association with hearing loss, harbors over 400 documented mutations that contribute significantly to non-syndromic hearing loss and are crucial for genetic screenings alongside genes like GJB2 and SLC26A4." (PMID 39596651, 2024). "This study has significantly expanded the spectrum of mutations associated with CDH23-linked hearing loss." (PMID 39287240, 2024). "From a treatment perspective, mouse models for CDH23-related non-syndromic hearing loss – C57BL/6J and salsa – exhibit a similar progressive hearing loss to that in humans." (PMID 39017633, 2024). "It is important to consider, however, the potential of certain gene mutations such as CDH23 or CHD7 – typically linked with syndromic forms of hearing loss – to directly affect central auditory pathways." (PMID 37697742, 2023). "Taken together, these findings suggest that the residual function defined by the CDH23 variants can cause various types of hearing loss, from non-syndromic to syndromic hearing loss as well as from congenital to age-related hearing loss." (PMID 35020051, 2022). "In the present large-cohort study, variants in CDH23 were shown to cause a broad spectrum of hearing loss: from non-syndromic to syndromic hearing loss as well as from congenital to age-related hearing loss." (PMID 35020051, 2022). "With regard to the progression of hearing loss in patients with CDH23 mutations, it is better to use long electrodes for CI/EAS that can cover low-frequency region." (PMID 35020051, 2022). "The present large-cohort study revealed that the prevalence of CDH23-associated hearing loss was 2.64% (307/11,594) among bilateral SNHL probands and 3.95% (273/6912) among ARSNHL/sporadic probands in this Japanese population." (PMID 35020051, 2022). "Based on the use of over 10,000 samples collected in a more unbiased manner, the present study indicated the prevalence of CDH23-associated hearing loss among non-syndromic SNHL patients." (PMID 35020051, 2022). "In fact, the MAF in Japanese controls is exceptionally high compared to those in other ethnic groups, which is consistent with the fact that there are many patients with CDH23-related hearing loss due to the founder effect." (PMID 35020051, 2022). "Variants in the CDH23 gene are responsible for both syndromic hearing loss (Usher syndrome type ID: USH1D) and non-syndromic hearing loss (DFNB12)." (PMID 35020051, 2022).